KRT78 (keratin 78)
Synonyms: CK-78; K78; K5B; KB40
Tractability: PROTAC: ubiquitination databases record sites on it.
Gene: Protein-coding gene on chromosome 12 (52,837,804 to 52,849,092, reverse strand). Ensembl gene ENSG00000170423.
Pathways (Reactome):
Developmental Biology: Differentiation of Keratinocytes in Interfollicular Epidermis in Mammalian Skin; Formation of the cornified envelope; Keratinization
Gene Ontology:
Molecular function: protein binding; structural constituent of skin epidermis
Biological process: intermediate filament organization; keratinization
Cellular component: extracellular exosome; extracellular region; cytosol; keratin filament
Genetic constraint (gnomAD): Loss-of-function variants: 55 observed, 50.71 expected, observed/expected ratio (o/e) 1.08, 90% interval 0.87 to 1.36. The upper end of that interval is the gene's LOEUF score, 1.36, which puts it in group 5 of 6, group 1 being the genes least tolerant of losing a copy. Missense variants: 649 observed, 666.27 expected, observed/expected ratio (o/e) 0.97, 90% interval 0.91 to 1.04. Synonymous variants: 289 observed, 272.97 expected, observed/expected ratio (o/e) 1.06, 90% interval 0.96 to 1.17.
Homologues: Orthologues: chimpanzee KRT78 (98% identical), macaque KRT78 (92% identical), pig KRT78 (79% identical), rabbit KRT78 (73% identical), rat Krt78 (69% identical), mouse Krt78 (68% identical), dog KRT78 (57% identical). Paralogues in human: KRT6A (54% identical), KRT5 (53% identical), KRT6B (53% identical), KRT6C (53% identical), KRT73 (53% identical), KRT3 (52% identical), KRT76 (52% identical), KRT75 (52% identical), KRT4 (51% identical), KRT1 (50% identical), KRT79 (50% identical), KRT71 (50% identical), and 56 more.
Diseases named in the same sentence as KRT78 in open-access papers:
KRT78 is named in the same sentence as 21 diseases in open-access papers, as found by Europe PMC text mining. Sharing a sentence is not in itself a finding about the gene and the disease. The quoted sentences say what the papers report.
cervical cancer (3 papers, 2018 to 2026). A primary or metastatic malignant neoplasm involving the cervix. "Cluster 8 was the most enriched for KRT78 and SERPINB2, both of which have been shown to exhibit increased expression in HPV‐associated cervical cancers." (PMID 41362277, 2026). "Although KRT78 has not previously been associated with prostate cancer, it has been identified as a diagnostic marker for metastatic melanoma and cervical cancers." (PMID 30296942, 2018).
head and neck squamous cell carcinoma (3 papers, 2023 to 2024). A squamous cell carcinoma that arises from any of the following anatomic sites: lip and oral cavity, nasal cavity, paranasal sinuses, pharynx, larynx, and salivary glands. "Particularly, the expression of Keratin 78 has been negatively correlated with inflammation and with the infiltration of macrophages in head and neck squamous cell carcinoma and in eosinophilic esophagitis." (PMID 38732018, 2024).
malignant melanoma (2 papers, 2018 to 2023). "The activation transcription factors, which regulate SPRR1A (small proline rich protein 1A), KRT78, claudin 4 and RAB25 (a member of the RAS oncogene family), also play crucial roles in malignant melanoma metastasis." (PMID 29377892, 2018).
urinary bladder cancer (2 papers, 2019 to 2023). A primary or metastatic malignant neoplasm involving the bladder. "And thirdly, we firstly identified a set of 4 genes (TMPRSS11E, SCEL, KRT78, TMEM185A) that were significantly associated with poor overall survival of bladder cancer patients, some of which have not been investigated in urinary bladder cancer before." (PMID 31737111, 2019).
esophageal squamous cell carcinoma (1 paper, 2015). Esophageal squamous cell carcinoma (ESCC) is a type of esophageal carcinoma (EC) that can affect any part of the esophagus, but is usually located in the upper or middle third. "KRT4, the keratin most evolutionarily similar to KRT78 in humans, is highly expressed in the esophagus and downregulated in esophageal squamous cell carcinoma." (PMID 26039063, 2015). "In an effort to gain insight into the potential function of KRT78, we performed phylogenetic analysis of all type II epithelial keratins and identified KRT78 as most closely related to keratin 4 (KRT4), which is downregulated in esophageal squamous cell carcinoma." (PMID 26039063, 2015).
keratoconus (1 paper, 2023). A degenerative, structural disorder of the eye, characterized by a cone-shaped protrusion of the cornea. "Among all the listed keratins only KRT1, KRT4, KRT76, and KRT78 are upregulated in keratoconus all the other keratins are not differentially expressed." (PMID 37279397, 2023).
psoriasis (1 paper, 2022). An autoimmune condition characterized by red, well-delineated plaques with silvery scales that are usually on the extensor surfaces and scalp. "KRT15, KRT24, KRT31, KRT37, KRT78 are differentially expressed in psoriasis, while KRT5 and KRT14 are specific for AD." (PMID 35874668, 2022).
tumor (6 papers, 2018 to 2025). "Notably, SPP1 expression increased markedly with higher tumor grades, while KRT78 expression decreased progressively with advancing cancer stages." (PMID 39596132, 2024). "Notably, among the hub genes, up-regulated SPP1 and down-regulated KRT78 expression significantly correlated with tumor grade, individual cancer stages, and poor survival in patients with HNSCC." (PMID 39596132, 2024). "Although the expression patterns of KRT80 and KRT78 appear similar, a closer examination reveals that KRT80 exhibits a thicker band of expression on the left, specifically within the tumor regions." (PMID 40236135, 2025). "We used Oncomine datasets (Ye Head‐Neck, and Peng Head‐Neck) to verify the expression levels of KRT13, KRT78, and SPRR3 in HNSCC tumor and normal tissues." (PMID 37092360, 2023).
cancer (5 papers, 2022 to 2025). A tumor composed of atypical neoplastic, often pleomorphic cells that invade other tissues. "Among the down-regulated hub genes, KRT78 expression displayed a significant association with individual cancer stages." (PMID 39596132, 2024). "Most of the genes showed an increase in gene expression during the stages of cancer, particularly in the last two stages, except for NDRG2, FAM3D, KRT78, SLURP1, MUC21, and CRCT1, which showed a significant drop in gene expression compared to normal tissue." (PMID 37917867, 2023).
KRT78 also shares sentences with these, for which no sentence is quoted: bacterial infections (1 paper); bladder cancer (1); colon adenocarcinoma (1); eosinophilic esophagitis (1); hepatocellular carcinoma (1); ischemia (1); ischemic stroke (1); kidney cancer (1); metastatic melanoma (1); neurodegenerative disease (1); prostate carcinoma (1); Stroke (1).